A2M (alpha-2-macroglobulin)
Diseases named in the same sentence as A2M in open-access papers (continued):
Sharing a sentence is not in itself a finding about the gene and the disease.
prostate carcinoma (9 papers, 2012 to 2021). A carcinoma that arises from epithelial cells of the prostate gland. "To confirm its neutralizing ability, we used 1LN prostate cancer cells, which highly express csGRP78 and in which α2M* was shown to induce a rapid increase in intracellular calcium." (PMID 34572299, 2021). "The interaction of α2M* and cell membrane-located GRP78 activates several signalling pathways implicated in cell survival, growth and proliferation in prostate cancer, which have been reported to promote syncytialisation in trophoblastic cells." (PMID 32541810, 2020). "To characterize the manner of epigenetic regulation by α2M* signaling, we treated a prostate cancer, glioblastoma, and melanoma cancer cell lines with C38 Mab and then stimulated with α2M* and acetate alone or in combination." (PMID 29296215, 2017). "In 1-LN prostate cancer cells, α2M* induced significant increase of H2A, H2B, H3, and H4 acetylation in a dose- and time-dependent manner." (PMID 29296215, 2017). "For example, ligation of cell surface GRP78 with α2M* promotes the proliferation of cancer cells in prostate cancer cells, blockade of cell surface GRP78 using the antibody against the COOH-terminal domain of GRP78 reverted the pro-proliferative effect of α2M*." (PMID 25958313, 2015). "Our initial studies demonstrated that the α2M*/CS-GRP78 axis regulates fatty acid synthesis and acetate uptake in prostate cancer cells." (PMID 29296215, 2017). "Autoantibodies from serum of prostate cancer patients against a segment of GRP78 (Leu 98-Leu115) induces cell proliferation, suggesting that these antibodies serve as agonists of activated α2-M, which recognizes the same site of GRP78." (PMID 28424579, 2017). "Our biotinylation results suggest that locally increased α2M* may facilitate the presentation of GRP78 on the cell surface in addition to its role as a ligand, as has also been shown in prostate cancer cells." (PMID 34572299, 2021). "In addition, α2M was reported to bind to the GRP78 receptor on the surface of the cell membrane, activating the IGFR and mTOR signaling pathways in prostate cancer, suggesting the involvement of the AKT/mTOR pathway in α2M-mediated cancer development." (PMID 32559179, 2020). "In addition, in highly metastatic and invasive 1-LN prostate cancers, cell-surface GRP78 acts as a receptor for activated α2-M leading to activation of PAK-2, and together with LIMK and cofilin phosphorylation, increases motility enhancing metastasis." (PMID 28424579, 2017).
COVID-19 (8 papers, 2021 to 2024). A disease caused by infection with severe acute respiratory syndrome coronavirus 2. "We identified that protein alpha-1-microglobulin/bikunin precursor (AMBP) and alpha-2-macroglobulin levels weresubstantially reduced in the COVID-19-with the AVB group." (PMID 39076308, 2024). "Our study revealed that COVID-19 patients that suffer from COVID-19 related thrombosis have a trend towards higher TG, reduced levels of thrombin inhibitor α2M, and an elevated plasmin generation lag time." (PMID 36248875, 2022). "We quantified plasma concentrations of C1-INH, AT, α2M and ITIH4, and identified multiple associations between protease inhibitor levels and COVID-19 severity." (PMID 34458849, 2021). "Recently, it was also hypothesized that A2M might confer some protection from COVID-19 through its ability to protect the vascular endothelium and potential antithrombin activity." (PMID 34970276, 2021). "Furthermore, although these findings require further investigation, they are immediately relevant to research of C1-INH and α2M in individuals with kidney impairment, including patients with COVID-19." (PMID 34458849, 2021). "However, further studies on the role of A2M in COVID-19, is needed to clarify this." (PMID 38957465, 2024). "Furthermore, the rebalancing of protease inhibitor levels, such as replenishing C1-INH or α2M, could be considered a therapeutic strategy for COVID-19." (PMID 34458849, 2021). "In contrast to the significant reduction of α2M levels in thrombosis patients, inflammatory marker CRP is elevated in COVID-19 patients." (PMID 36248875, 2022). "Plasma C1-INH (P = 0.01) and α2M (P = 0.001) were lower and total ITIH4 (P = 0.003) were higher in COVID-19 patients." (PMID 34458849, 2021). "Analysis of all available samples demonstrated lower plasma C1 esterase inhibitor and α2M and higher total ITIH4 in COVID-19 compared with dialysis controls." (PMID 34458849, 2021). "We identified lower plasma concentrations of C1-INH (P = 0.0003) and α2M (P = 0.0002) and higher plasma concentrations of total ITIH4 (P = 0.008) in COVID-19 samples." (PMID 34458849, 2021). "Another important factor, plasma α2M levels, is both an acute phase reactant and a thrombin inhibitor, and to our knowledge has not previously been investigated in COVID-19 patients." (PMID 36248875, 2022). "We identified reduced C1-INH and α2M and raised total ITIH4 levels in COVID-19 samples." (PMID 34458849, 2021). "We identified significantly greater plasma C1-INH and α2M levels in haemodialysis patients without COVID-19 than healthy controls." (PMID 34458849, 2021).
breast carcinoma (7 papers, 2011 to 2023). "In our study, alpha-2-macroglobulin and ceruloplasmin were both lower in pre-diagnostic breast cancer samples compared to the control samples." (PMID 21871081, 2011). "With 2D-nanoLC-MS/MS, afamin, apolipoprotein E and isoform 1 of inter-alpha trypsin inhibitor heavy chain H4 (ITIH4) were found to be higher in pre-diagnostic breast cancer (p < 0.05), while alpha-2-macroglobulin and ceruloplasmin were lower (p < 0.05)." (PMID 21871081, 2011). "Of the proteins detected with 2D-nanoLC-MS/MS, afamin, apolipoprotein E and an isoform of ITIH4 were slightly, but significantly higher and alpha-2-macroglobulin and ceruloplasmin slightly, but significantly lower in pre-diagnostic breast cancer samples compared to control samples." (PMID 21871081, 2011). "Considering the oncogenic role of GALNT6 in promoting metastasis, α2M was selected for further investigation as an important substrate in breast cancer metastasis in current study." (PMID 32559179, 2020). "GALNT6 was shown to promote metastasis of breast cancer cells by enhancing mucin-type O-glycosylation, and α2M was identified as a novel substrate of GALNT6 in the secretory supernatant of breast cancer cells." (PMID 32559179, 2020). "In the 1980s however, the acute phase proteins alpha-2-macroglobulin and ceruloplasmin were already studied in relation to breast cancer, using immunoassay methods." (PMID 21871081, 2011). "The unique properties of alpha-2-macroglobulin confirmed that the increased level of this protein in the plasma of hibernating common carp may have anti-cancer effects on breast cancer cells in this study." (PMID 35190572, 2022). "Furthermore, we identified α2-macroglobulin (α2M) as a GALNT6 substrate and showed that GALNT6-mediated α2M glycosylation could promote metastasis via the AKT signaling pathway in breast cancer cells." (PMID 32559179, 2020). "However, there may be different mechanisms underlying the anti-cancer effects of hibernating common carp plasma on breast cancer cells, our findings demonstrated the increased level of alpha-2-macroglobulin in plasma of this fish during hibernating could be a key factor." (PMID 35190572, 2022). "Further investigation showed that GALNT6 increased O-glycosylation of α2M, and the following activation of the downstream PI3K/Akt signaling pathway was involved in the promotion of migration and invasion of breast cancer cells." (PMID 32559179, 2020). "In summary, our study demonstrates that GALNT6 can promote metastasis by increasing mucin-type O-glycosylation of α2M, and activating the downstream PI3K/Akt signaling pathway in breast cancer cells." (PMID 32559179, 2020). "Interestingly, we observed that one set of proteins was identified more frequently, with HLA-A, HLA-B, A2M, ACTB, ALDOA, ANXA2, and FN1 identified in at least 13 of 22 studies that explored the vesicular proteome in breast cancer." (PMID 37629204, 2023). "As α2M and CBFA2T2 showed relatively high expression, whilst AHSG and hornerin showed extremely low expression in MDA-MB-231 and MDA-MB-468 cells, we speculated that α2M and CBFA2T2 may play key roles in GALNT6-mediated metastasis of breast cancer." (PMID 32559179, 2020).
melanoma (7 papers, 1980 to 2025). A malignant, usually aggressive tumor composed of atypical, neoplastic melanocytes. "In the present study, we developed a prognostic and diagnostic biomarker with 5 selected MRGs (A2M, DUSP6, HLA-B, SERPINE2, and SLC26A2), all of which acted as risk factors in melanoma." (PMID 33324561, 2020). "A2M was found to be expressed in many different cancers like human gliomas, melanomas, colon cancer etc. indicating its role in tumorigenicity." (PMID 28469129, 2017). "From the microarray results, the three genes (α-2-macroglobulin (A2M), collagen type II alpha-1 (Col2A1), melanoma inhibitory activity-1 (MIA)) showing the highest upregulation or fold change were selected for validation by means of RT-PCR." (PMID 20579363, 2010). "Single serum samples from 59 melanoma patients and age- and sex-matched controls were further examined for sialic acid, alpha 1-acid glycoprotein, alpha 1-antitrypsin, haptoglobin, and alpha 2-macroglobulin." (PMID 6158966, 1980). "The immunohistochemical results of the Human Protein Atlas dataset demonstrated that four hub genes (A2M, NAMPT, LIF, and ERAP1) are overexpressed in melanoma tissues." (PMID 35326741, 2022). "A2M has been shown to upregulate the tumour suppressor PTEN and inhibit cell proliferation in various cancer cell lines, including melanoma, suggesting a tumour‐inhibitory mechanism that could be therapeutically exploited." (PMID 41017066, 2025). "The results demonstrated that EBI3, ERAP1, and NAMPT mRNA levels were upregulated in melanoma tissues, while A2M and LIF were not insignificant." (PMID 35326741, 2022).
nephrotic syndrome (6 papers, 2015 to 2024). A collection of symptoms that include severe edema, proteinuria, and hypoalbuminemia; it is indicative of renal dysfunction. "A2M plays an important role in nephrotic syndrome and FSGS, being upregulated in glomerular endothelial cells and showing elevated plasma levels in nephrotic patients to balance oncotic pressure when serum albumin is lost." (PMID 39125467, 2024). "Alfa-2-macroglobulin (A2M) is known to be elevated in patients with nephrotic syndrome—we have also found its excessive abundance in the plasma of CKD patients, again peaking at stage 2." (PMID 35884827, 2022). "Elevated plasma levels of alpha-2-macroglobulin, along with Fibrinogen and albumin levels, is commonly seen in nephrotic syndrome." (PMID 31159152, 2019). "Interestingly, increased A2M levels are detected in some nephrotic syndromes indicating the important role of A2M in kidney." (PMID 29464020, 2018).
type 2 diabetes (6 papers, 2015 to 2023). "One study showed a correlation between urinary α2M levels and the degree of microalbuminuria in individuals with type 2 diabetes." (PMID 34572299, 2021).
diabetic retinopathy (5 papers, 2013 to 2020). "Studies have demonstrated that TIMP1 and A2M expression is increased in the eyes of patients or animals with diabetic retinopathy." (PMID 29318137, 2017). "Alpha 2-macroglobulin has been suggested to be a potential biomarker for diabetic retinopathy and other diabetic complications." (PMID 27280065, 2016). "Moreover, the onset of some diseases, such as periodontitis, diabetic retinopathy and inflammatory joint disease results in increased activated α2M levels in other extracellular fluids." (PMID 23353684, 2013). "In fact, high-throughput sequencing indicated that the coexpressed gene, A2M (A2MD|CPAMD5|FWP007|S863-7) which encodes the α-2-macroglobulin that acts as a carrier of proinflammatory cytokines such as interleukin-1β, interleukin-6, and tumor necrosis factor-α, causes diabetic retinopathy." (PMID 32148491, 2020).
glioblastoma (5 papers, 2014 to 2024). The most malignant astrocytic tumor (WHO grade IV). "Moreover, it was found that A2M has a moderate upregulation in almost all cancers except glioblastoma multiforme (GBM), head and neck squamous cell carcinoma (HNSC), and stomach adenocarcinoma (STAD)." (PMID 39434140, 2024). "We conducted α2M–RG internalization assays using seven cell lines derived from different origins: HEK293 (embryonic kidney), HeLa (cervical cancer), A549 (lung cancer), U2OS (osteosarcoma), Huh7 (liver carcinoma), HCT116 (colon cancer), and T98G (glioblastoma)." (PMID 36977730, 2023). "Interestingly, expression levels of many serum proteins including thrombispondin-I, serotransferrin, and alpha-2-macroglobulin were found to be altered in meningioma patients, but not reported in glioblastomas (GBMs)." (PMID 25413266, 2014).
liver disease (5 papers, 2009 to 2025). "Clinically, Apo-A1 is routinely combined with alpha-2-macroglobulin (A2M) and haptoglobin (HP) to facilitate monitoring of the progression of the liver disease." (PMID 40809427, 2025). "Reduced transferrin and increased alpha-2-macroglobulin in HBV carriers might suggest active liver disease." (PMID 19860894, 2009).
lung cancer (5 papers, 2019 to 2026). A malignant neoplasm involving the lung. "A2M was identified as a key gene associated with various tumors, including non–small cell lung cancer, bladder cancer, osteosarcoma, and HCC." (PMID 33613623, 2020). "In a panel of lung cancer cell lines with varying degrees of paclitaxel resistance, TMEM243 was also recognized as a paclitaxel resistance inducer whose expression rises in parallel with the loss of the tumor suppressor protein alpha-2-macroglobulin (A2M)." (PMID 41596760, 2026).
mastitis (5 papers, 2014 to 2024). Inflammation of breast tissue during lactation or postpartum due to an obstructed duct or infection. "A2M protein belongs to the complement and coagulation cascades pathway, which has been reported that it is involved in the mastitis susceptibility in our previous publication." (PMID 25273983, 2014). "Alpha-2-macroglobulin (A2M) has been reported to bind host or foreign peptides and particles, thereby serving as a defensive barrier in mastitis." (PMID 36458189, 2022). "In summary, TMT analyses elucidated the role of A2M, Itgb2, Thbs1, Fn1, ITIH4 and other proteins in the host innate response to S. aureus-induced mastitis." (PMID 32365127, 2020).
osteosarcoma (5 papers, 2020 to 2024). A usually aggressive malignant bone-forming mesenchymal neoplasm, predominantly affecting adolescents and young adults. "A previous study reported that A2M upregulation is related to metastasis in osteosarcoma and to ovarian carcinogenesis." (PMID 32352014, 2020). "Although seldom previous studies have revealed the expression and role of VAMP8, APOC1 and A2M in osteosarcoma, exploration in some other tumors has well proved that these genes are important tumor-related regulatory factors." (PMID 32665038, 2020). "VAMP8, A2M, HLA-DRA, SPARCL1, HLA-DQA1, APOC1 and AQP1 were identified continuously upregulating during the oncogenesis and metastasis of osteosarcoma." (PMID 32665038, 2020).
bladder cancer (4 papers, 2020 to 2023). "a2M (alpha-2-macroglobulin) has been reported to be upregulated in the urine exosomes of bladder cancer patients." (PMID 37805491, 2023). "The potential of alpha-2-macroglobulin (A2M) and clusterin (CLU) as novel diagnostic urinary EV (uEV) biomarkers for bladder cancer (BC) was demonstrated previously." (PMID 37676879, 2023). "Our previous study demonstrated the potential of alpha-2-macroglobulin (A2M) and clusterin (CLU) as novel diagnostic uEV biomarkers for bladder cancer (BC) through a comparative analysis of uEVs acquired from patients with BC before and after surgery using an antibody array." (PMID 37676879, 2023).
Cirrhosis (4 papers, 2006 to 2021). A chronic disorder of the liver in which liver tissue becomes scarred and is partially replaced by regenerative nodules and fibrotic tissue resulting in loss of liver function. "However, the effect of elevated α2M levels in cirrhosis patients on TG itself was negligible and statistically insignificant." (PMID 28472132, 2017). "We observe lower intensities in the non-fucosylated glycopeptides of proteins (hemopexin, clusterin, ITIH4, fibrinogen) reported to decrease in cirrhosis while the non-fucosylated glycopeptide of alpha-2 macroglobulin has higher intensity in cirrhosis in line with its increased serum concentration." (PMID 34857845, 2021).
fibrosis (4 papers, 2011 to 2023). the formation of excess fibrous connective tissue in an organ or tissue in a reparative or reactive process. "The analysis of the nine genes, namely A2m, Akr7a3, Aqp7, Ca3, Cdc2a, Cdkn3, Cyp2c11, Ntf3, and Sds, revealed the association between NGHCs and chronic inflammatory liver conditions, including liver cirrhosis and fibrosis." (PMID 32560183, 2020). "Mac-2-binding protein, alpha-2-macroglobulin and hemopexin levels were found increased while A-1-antitrypsin, leucine-rich alpha-2-glycoprotein and fetuin-A were decreased in advanced fibrosis F4 as compared to early fibrosis F0/F1." (PMID 21299910, 2011). "A new score, NIS4TM, uses the biomarkers of miR-34a, alpha-2 macroglobulin, YKL40, and HbA1C to detect active steatohepatitis and advanced fibrosis (NAFLD activity score ≥4 and fibrosis ≥2)." (PMID 32933184, 2020). "Fibrospect is based on an algorithm encompassing the concentrations of three serum markers, alpha-2 macroglobulin (A2M), hyaluronic acid (HA), and tissue inhibitor metallopeptidase protein 1 (TIMP1), to differentiate NAFLD patients with advanced fibrosis from those with milder forms of fibrosis." (PMID 32933184, 2020).
liver cirrhosis (4 papers, 2017 to 2020). "Furthermore, we hypothesized that the increase in α2M level in liver cirrhosis could compensate for the AT deficiency to some extent." (PMID 28472132, 2017). "On the contrary, in subjects with low AT levels or high α2M levels, such as liver cirrhosis patients and young children, the balance between T-AT and T-α2M has been shown to shift in favor of T-α2M complexes." (PMID 32719370, 2020). "In complex diseases, such as liver cirrhosis, coagulation is altered at many points which have opposite effects on thrombin generation (e.g. increase of α2M and FVIII, and a decrease of FII and AT)." (PMID 28472132, 2017). "Our study confirms previous reports that AT and prothrombin levels are reduced in patients with liver cirrhosis and that α2M levels are increased." (PMID 28472132, 2017). "In silico experimentation shows that the increase of α2M levels in liver cirrhosis significantly improved the thrombin decay capacity, although it could not be restored to the level found in healthy subjects." (PMID 28472132, 2017).
Obesity (4 papers, 2021 to 2026). Accumulation of substantial excess body fat. "This analysis identified proteins not previously associated with childhood obesity, to the best of our knowledge, including A2M, PON3, ADAMTSL4, HSPG2 and MAGEB6B, all of which showed decreased levels in children with obesity." (PMID 39972214, 2025). "BMI-predictive proteins included established obesity markers and obesity-related proteins, including adiponectin, CRP, IGFBP1, IGFBP2, PRG4, SHBG, apolipoproteins (APOA4, APOF) and inflammatory response proteins (A2M, APCS, LBP, HSPG2, HP, AOC3, ITGB1, VNN1)." (PMID 39972214, 2025).